TLR1 (toll like receptor 1)
Diseases named in the same sentence as TLR1 in open-access papers (continued):
Sharing a sentence is not in itself a finding about the gene and the disease.
pneumonia (11 papers, 2016 to 2025). An acute, acute and chronic, or chronic inflammation focally or diffusely affecting the lung parenchyma, caused by an infection in one or both of the lungs (by bacteria, viruses, fungi, or mycoplasma.). "The aim of the study was to determine the molecular genetic prognostic criteria for the severity of pneumonia based on the analysis of the association of genetic polymorphisms of toll-like receptors (rs5743551 (TLR1), rs5743708 (TLR2), and rs4986790 (TLR4) loci) with the severity of NETosis." (PMID 34603755, 2021). "A comparative analysis of the genotype/allele frequencies for the rs5743551 (TLR1), rs5743708 (TLR2), and rs4986790 (TLR4) polymorphisms was carried out depending on the outcome of pneumonia (recovery/death)." (PMID 34603755, 2021). "Further investigation of the effect of TLR1 and TLR4 polymorphisms in the immunological response in pneumonia is needed." (PMID 34603755, 2021). "The aged mice also express lower levels of TLR1, TLR6, and TLR9 in the lungs, which also increases their susceptibility to pneumonia." (PMID 32849610, 2020). "During pneumonia, AECs recognize various pathogens due to the expression of different PRRs, including TLRs [TLR1, TLR2, TLR4, TLR5, TLR6 (Extracellular TLRs), and TLR3, TLR7, TLR8, and TLR9 (Intracellular TLRs)] and NLRs comprising inflammasome." (PMID 32849610, 2020). "The results from this study showed that serum zinc status was associated with altered cytokine responses to various toll-like receptor ligands (TLR1/2, 4, 7/8) and infectious diseases (pneumonia and enterocolitis) in a prospective cohort of children who were mostly zinc-sufficient." (PMID 36558553, 2022). "In Baladi goats with pneumonia and healthy control group, PCR-DNA sequencing revealed SNPs linked to pneumonia susceptibility and resistance in immunological genes (SLC11A1, CD-14, CCL2, TLR1, TLR7, TLR8, TLR9, defensin, SP110, SPP1, BP1, A2M, ADORA3, CARD15, IRF3, and SCART1)." (PMID 40221769, 2025). "The immune genes’ mRNA levels in goats (SLC11A1, CD-14, CCL2, TLR1, TLR7, TLR8, TLR9, defensin, SP110, SPP1, BP1, A2M, ADORA3, CARD15, IRF3, and SCART1) varied between the healthy and infected goats with pneumonia." (PMID 40711280, 2025). "Significant results were obtained when comparing the samples obtained from individuals with pneumonia before the spread of SARS-CoV-2 and from the controls for rs5743551 (TLR1) and rs3764880 (TLR8)." (PMID 36611413, 2022). "Through PCR-DNA sequencing in Baladi goats with and without pneumonia, SNPs linked to pneumonia susceptibility and resistance were discovered in the immunological (SLC11A1, CD-14, CCL2, TLR1, TLR7, TLR8, TLR9, defensin, SP110, SPP1, BP1, A2M, ADORA3, CARD15, IRF3, and SCART1) genes." (PMID 40711280, 2025). "The levels of immunological genes (SLC11A1, CD-14, CCL2, TLR1, TLR7, TLR8, TLR9, defensin, SP110, SPP1, BP1, A2M, ADORA3, CARD15, IRF3, and SCART1) vary in goats with and without pneumonia." (PMID 40221769, 2025). "Real-time PCR was conducted to quantify the expression levels of immunological markers (SLC11A1, CD-14, CCL2, TLR1, TLR7, TLR8, TLR9, β defensin, SP110, SPP1, BP1, A2M, ADORA3, CARD15, IRF3, and SCART1) in Baladi goats with and without pneumonia resistance." (PMID 36977224, 2023).
Arthritis (10 papers, 2009 to 2025). Inflammation of a joint. "Strle and coworkers also showed that TLR1 polymorphisms in some human patients triggered an exacerbated Th1 inflammatory response, especially in those with antibiotic refractory arthritis." (PMID 23024745, 2012). "Patients infected with B. burgdorferi strain 16s–23s rRNA intergenic spacer type (RST) genotype 1 with the TLR1 polymorphism (TLR1-1805GG) have a stronger Th1-like inflammatory response, suggesting an increased susceptibility to antibiotic-refractory arthritis." (PMID 40732111, 2025). "We found that patients with post-infectious Lyme arthritis, a condition characterized by marked persistent synovitis in joints, have a higher frequency of TLR1-1805GG compared to those whose arthritis resolves with antibiotics." (PMID 41333458, 2025). "We comparatively analyzed the expression of TLR1 through TLR9 in synovium during the whole course of arthritis initiation and development to investigate the roles of TLRs systematically and dynamically in a PIA model." (PMID 21708001, 2011). "In the present study, we tried to find the key TLR in arthritis development by screening the TLR1-9 expression profile in spleen from PIA rats." (PMID 20500834, 2010). "The fact that TLR4 and TLR1 may be involved in the pathogenesis not only of RA but also of other forms of arthritis, including OA, is also indicated by the correlation analysis between clinical parameters and TLR gene expression." (PMID 35126351, 2021). "Screening TLR mRNA expression at different time points after pristane injection, we found that expression of TLR1, 2, 3, 4 and 8 in the spleen is upregulated in the development stage of arthritis (d26), which is consistent with previous studies from arthritis models and RA patients." (PMID 20500834, 2010). "Using an online Venn diagram tool, we then screened four genes related to dysregulated genes shared by TGT’s active ingredients and SLE and arthritis, including NLRC3, CD96, CCL2, and TLR1." (PMID 37312878, 2023). "To find out the candidate key TLR, we analyzed TLR1 through TLR9 mRNA expression in the synovium of PIA rats at different time points, including D0 (normal phase), D6 (prearthritis phase), D12 (arthritis onset phase) and D26 (acute arthritis phase)." (PMID 21708001, 2011).
atherosclerosis (10 papers, 2008 to 2025). A disease characterized by the build-up of fatty material and calcium deposition in the arterial wall resulting in partial or complete occlusion of the arterial lumen. "The expression of CD254 is associated with calcification and plaque rupture and CD281 (Toll- like receptor-1) reflect the activate state of macrophages or foam cells in phagocytosing foreign particles like lipid in the area of atherosclerosis." (PMID 24551082, 2014). "Toll-like receptor 1 (TLR1) was found to exhibit increased expression in aged mouse brain, and chemokine receptor 5 (CCR5) has been associated with atherosclerosis and Alzheimer’s disease." (PMID 23947592, 2013). "A deficiency in either TLR6 or TLR1 did not reduce atherosclerosis disease induced by exposure to a high fat diet, all together suggesting that TLR6 and TLR1 individually may not be sufficient per se, but will act together with TLR2 as heterodimers." (PMID 23880853, 2013). "The expression levels of TLR1, TLR2, and TLR4 were found elevated in human and experimental models of atherosclerosis." (PMID 31565149, 2019). "TLR2/TLR1 specific small molecule inhibitors have been recently identified and will be worth screening in animal models of AMD, angiogenesis, and atherosclerosis." (PMID 25184331, 2014).
breast carcinoma (9 papers, 2013 to 2024). "Decreased levels of CASP8, DDX58, CPNE1, ULK3, PARK7, and BTN2A1, as well as increased levels of TNFRSF9, TNXB, DNPH1, and TLR1, were linked to an elevated risk of breast cancer." (PMID 39351539, 2024). "We found that genetically lower levels of CD160 and LRRC37A2 and genetically higher levels of DNPH1, LAYN and TLR1 were associated with increased risk of breast cancer." (PMID 37996402, 2023). "In conclusion, by applying an MR approach to a broad range of circulating proteins we found that genetically elevated CD160, DNPH1, LAYN, LRRC37A2 and TLR1 were associated with breast cancer." (PMID 37996402, 2023). "Of those, we present five proteins (CD160, DNPH1, LAYN, LRRC37A2 and TLR1) that show a potential causal role in breast cancer risk with confirmatory results in independent cohorts." (PMID 37996402, 2023). "To summarise, the MR analysis showed that genetic elevation of CD160, DNPH1, LAYN, LRRC37A2 and TLR1 associated with breast cancer risk, and with similar effects on ER+ and ER− cancers." (PMID 37996402, 2023). "Moreover, analysis of the gene expression datasets of breast cancer brain metastasis patients revealed associations of TLR1 and IL6 with poor overall survival." (PMID 36224342, 2022). "To test this hypothesis, we evaluated the association of rs3775291 in TLR3 and rs4833095 in TLR1 with breast cancer survival in 715 primary breast cancer patients in a cohort of prospectively observed Chinese patients." (PMID 26226228, 2015). "Our study aimed to explore the possible effects of the SNPs rs3775291 in TLR3 and rs4833095 in TLR1 on the prognosis of breast cancer patients." (PMID 26226228, 2015). "In this prospective observational study, rs3775291 in TLR3 and rs4833095 in TLR1 were genotyped in 715 patients with primary breast cancer in a Chinese population." (PMID 26226228, 2015). "TLR1 exhibited PPI with current breast cancer therapeutic targets." (PMID 38887235, 2024). "Lead pQTL in cis-regions for CD160, LAYN and TLR1 were not the variants with the lowest p-values for breast cancer risk but were localised in the same, size-limited, genomic region." (PMID 37996402, 2023). "Here, we hypothesized that genetic variants in TLR1 and TLR3 may be associated with breast cancer outcome." (PMID 26226228, 2015). "Taken together, these findings suggest that rs4833095 may not affect the function of TLR1, and thus may not be associated with breast cancer RFS." (PMID 26226228, 2015). "Here, we investigated the association of two missense SNPs, rs3775291 (c.1234G>A) in the TLR3 gene and rs4833095 (c.743T>C) in the TLR1 gene, with relapse-free survival (RFS) in a cohort of prospectively observed breast cancer patients." (PMID 26226228, 2015).
colitis (8 papers, 2017 to 2025). Inflammation of the colon. "Other TLR mutations, including those TLRs analysed here (TLR1, -2, -4, -6), have been linked to a broad spectrum of immune disorders and chronic infections, such as colitis in mice and common variable immunodeficiency, asthma, Crohn's disease, atherosclerosis, tuberculosis and leprosy in humans." (PMID 37997696, 2023). "In addition, in a mouse model of colitis, L. johnsonii has been shown to alleviate the associated symptomatology through the activation of anti-inflammatory macrophages and stimulation of IL-10 production via the TLR1/2-STAT3 pathway." (PMID 40869018, 2025). "Tlr1 knockout mice exhibit decreased proliferation rates in the colonic crypt and impaired recovery of the tissue after colitis induction." (PMID 37997696, 2023). "The aim of this study was to determine the impact of TLR1, TLR2, and TLR6 deficiency on inflammatory parameters associated with C. albicans colonization and acute colitis induced by DSS by comparing wild-type, TLR1−/−, TLR2−/−, and TLR6−/− mice." (PMID 28289440, 2017). "The dominance of Lactobacillus johnsonii in HP group correlates with its unique capacity to polarize resident macrophages toward an immunoregulatory CD206+ phenotype and mediates IL-10 secretion via the TLR1/2-STAT3 signaling axis to ameliorate experimental colitis." (PMID 41154565, 2025). "In addition to the NOD2 pathway, L. johnsonii was reported to activate TLR1/2 in macrophages for relieving colitis, suggesting that other immune signaling pathways be involved in the interaction between this symbiont and host." (PMID 39574408, 2025). "L. johnsonii could activate native macrophages into CD206+ macrophages and release IL-10 through TLR1/2-STAT3 pathway to relieve experimental colitis." (PMID 36398889, 2022). "In this study, we explored whether the deficiency in TLR1, TLR2 or TLR6 impacts C. albicans colonization and inflammation-associated colonic injury in the dextran sulfate sodium (DSS)-induced colitis in mice." (PMID 28289440, 2017). "Additionally, a recent study demonstrated that Tlr1 and Tlr2 (but not Tlr6) knockout mice display increased intestinal permeability and pathogenic yeast colonisation in a colitis model." (PMID 37997696, 2023). "CBLB502, a slightly modified version of KMRC011, significantly downregulates the TLR1, 2, 3, 4, 6, 7, 8, and 9 mRNA expression levels and had therapeutic effect in TNBC-induced colitis model by altering the NF-κB signaling pathway." (PMID 36457188, 2023). "In conclusion, we identified that L. johnsonii could promote the activation of CD206+ macrophagesIL-10 through TLR1/2-STAT3 pathway, and relieved experimental colitis." (PMID 36398889, 2022). "Additionally, the bacteriocin it secretes (e.g., lactocin Johnsonii) can activate naive macrophages to differentiate into CD206+ macrophages and induce the release of IL-10 via the TLR1/2-STAT3 pathway, alleviating experimental colitis and further enhancing anti-inflammatory and probiotic effects." (PMID 41463870, 2025).
melanoma (8 papers, 2009 to 2024). A malignant, usually aggressive tumor composed of atypical, neoplastic melanocytes. "For instance, the application of TLR1/2 agonists (Diprovocim) can effectively enhance the therapeutic effect of PD-1 immunotherapy and prolong the survival time of mice in melanoma." (PMID 34858419, 2021). "Depletion of Tregs was also associated with an improved efficacy of anti-CTLA-4 treatment combined with TLR1/2 (Toll-like receptor 1/2) ligands in the murine model of melanoma." (PMID 32517213, 2020). "Our syngeneic colon model CT26 had more infiltration of Tregs than the melanoma Model B16F1050,51, which may influence the impact of TLR1/2 agonists on the immune status within the TME." (PMID 37945630, 2023). "Similarly, an anti-tumor vaccine combined with TLR1/2 therapy was found to significantly enhance anti-tumor immunity by decreasing PD-1 expression and inducing antigen-specific CD8 + T cells in a mouse melanoma model." (PMID 34654352, 2021).
Candidemia (7 papers, 2014 to 2024). A form of invasive candidiasis where species of CANDIDA are present in the blood. "Additionally, in agreement with our results, TLR1 gene polymorphisms have been associated with an increased susceptibility to candidemia in patients." (PMID 28289440, 2017). "While TLR1 polymorphisms have been recently shown to influence susceptibility to candidemia, no such effect was apparent in patients with RVVC." (PMID 25295030, 2014). "In a study of 338 patients with severe invasive candida infection (candidemia) and 351 non-infected controls, Plantiga and colleagues found 3 TLR1 SNPs (R80T, S248N and I602S) that were significantly associated with susceptibility to candidemia, particularly in white individuals." (PMID 34199501, 2021).
autoimmune disease (6 papers, 2012 to 2025). A disorder resulting from loss of function or tissue destruction of an organ or multiple organs, arising from humoral or cellular immune responses of the individual to their own tissue constituents. "Previous research has demonstrated that TLR1 plays a crucial role in the occurrence and development of various diseases, including infectious diseases, autoimmune diseases, and cancer." (PMID 38573314, 2024). "Additional Ets1 target genes include ones important for immune function such as Il5ra, Tlr1, Traf4, and Ltk, but that not yet been implicated as susceptibility loci for autoimmune disease." (PMID 28439269, 2017). "Notably, both HLA-I-specific and HLA-II-specific pGenes included known drug targets for autoimmune diseases, infectious diseases, and cancer such as LAG3, PDCD1, TNF, and ACE2 affected by HLA-I; and IL18, TREM2, VSIG4, and TLR1 by HLA-II." (PMID 39085222, 2024).
colorectal cancer (6 papers, 2014 to 2025). A primary or metastatic malignant neoplasm that affects the colon or rectum. "Colorectal cancer tissues have higher TLR1, TLR2, TLR4 and TLR8 gene expression levels in general than do the normal colon mucosa from the same patient (p < 0.05)." (PMID 25547486, 2014). "Moreover, direct coculture of OXP-treated colorectal cancer cells with defective TLR1-iDCs showed that DC maturation and T-cell activation were remarkably attenuated in vitro, suggesting that TLR1 is essential for the HMGB1-TLR2 axis to boost antitumor immunity." (PMID 37945630, 2023). "Toll-like receptors (TLRs), particularly TLR1, TLR2, and TLR4, play a multifaceted role in the progression of colorectal cancer (CRC)." (PMID 41419456, 2025).
pulmonary TB (6 papers, 2013 to 2024). "In our study, a PSS identified in TLR1 in perissodactyls (Y309Q, H) corresponded to the H305L site associated with pulmonary tuberculosis in humans." (PMID 37874499, 2024). "In conclusion, we have identified a variant, TLR1 H305L, that strongly confers protection from pulmonary TB." (PMID 27214039, 2016). "Patients with active pulmonary TB showed increased TLR1, 2, 4 and 6 mRNA levels in whole blood leukocytes when compared with healthy controls, while TLR 7 and 9 mRNA expression was unaltered." (PMID 25887604, 2015).
aspergillosis (5 papers, 2015 to 2024). Aspergillosis is an infection, growth, or allergic response caused by the Aspergillus fungus. "Of note, several polymorphisms of human TLRs, e.g., TLR1, TLR2, TLR4, TLR6, or TLR9, have been associated with increased risk of invassive aspergillosis in susceptible hosts." (PMID 29081774, 2017). "Therefore, polymorphisms of many immune-related genes are associated with susceptibility to aspergillosis, such as tumor necrosis factor receptor 1 (TNFR1), TLR1/4/5/6, Dectin-1, DC-SIGN, IL-8, IL-10, IL-12, IL-4R, IFN-γ, IRF4 and so on." (PMID 35407478, 2022).
atopic asthma (5 papers, 2013 to 2025). An asthma that is characterized by symptoms that are triggered by an allergic reaction caused by inhaled allergens such as dust mite allergen, pet dander, pollen and mold. "In a large German study, a protective effect of genetic variants on atopic asthma was identified in the TLR2-associated heterodimer network consisting of TLR1, TLR6, and TLR1012." (PMID 28592890, 2017). "Interestingly, genetic variants within the TLR2-associated heterodimer network (including TLR1 and TLR6) confer strong protection against atopic asthma." (PMID 40672946, 2025). "For TLR1, rs5743595, rs4833095, and not rs5743594 showed significant inverse effects with atopic asthma in childhood." (PMID 23496969, 2013). "In that report, PBMCs of atopic asthma patients carrying −2192C showed increased expression of TLR1 mRNA and protein, increased production of proinflammatory cytokine TNF-α and TH1 cytokines IL-12 and IFN-γ, and decreased production of TH2 cytokine IL-4 after stimulation with TLR1/2 ligand Pam3CSK4." (PMID 27727278, 2016).
atopic eczema (5 papers, 2016 to 2021). A common chronic pruritic inflammatory skin disease with a strong genetic component. "eSkIN also shows that TLRs (TLR1 and TLR2), which are known to promote atopic dermatitis, are downregulated by BM." (PMID 29415693, 2018).